PAX2 (paired box 2)
Diseases named in the same sentence as PAX2 in open-access papers (continued):
Sharing a sentence is not in itself a finding about the gene and the disease.
optic nerve abnormalities (1 paper, 2010). "Because mutation of PAX2 in humans is known to result in congenital optic nerve abnormalities, we considered it an excellent candidate gene." (PMID 20221250, 2010).
ovarian endometriosis (1 paper, 2025). A non-neoplastic disorder characterized by the growth of endometrial tissue in the ovaries. "Marker aberrance was rare in ovarian endometriosis without atypia, limited to a single case (1/32) aberrant for only PAX2." (PMID 39078313, 2025).
ovarian teratoma (1 paper, 2019). A non-seminomatous germ cell tumor arising from the ovary. "In summary, we firstly reported skeletal deformity (fourth metatarsal microsomia), ovarian teratoma, and congenital ventricular septal defect as new phenotypes of PAX2‐related disorder which enlarged the phenotypic spectrum." (PMID 31060108, 2019). "We firstly reported skeletal deformity (fourth metatarsal microsomia), ovarian teratoma, and congenital ventricular septal defect as new phenotypes of PAX2‐related disorder which enlarged the phenotypic spectrum." (PMID 31060108, 2019).
Proteinuria (1 paper, 2022). Increased levels of protein in the urine. "Proteinuria is the most common kidney manifestation in children with PAX2 variants." (PMID 35444690, 2022).
retinal disease (1 paper, 2022). "PAX2 is within the current, widely available inherited retinal disease gene sequencing panels." (PMID 36249605, 2022).
Retinal dysplasia (1 paper, 2025). Abnormal growth and differentiation, structure and appearance of the retina present from birth. "The PAX2 p.(Arg252*) genetic variant was reported in a series of severe prenatal CAKUT; a fetus with bilateral hyperechogenic kidneys, hypoplasia with cortical tubular microcysts, and focal retinal dysplasia." (PMID 40282888, 2025).
salivary gland tumors (1 paper, 2024). "While some of these markers can be found in salivary gland tumors, PAX-2, PAX-8, and hKIM-1 typically show negative reactivity in such tumors." (PMID 39931206, 2024).
serous cystadenoma (1 paper, 2019). A serous neoplasm in which the cysts and papillae are lined by a single layer of cells without atypia, architectural complexity or invasion. "The acquisition of KRAS or BRAF and possibly other mutations including PAX-2 in OEIs and serous cystadenomas result in their gradual transformation to serous borderline tumors and ultimately LGSC." (PMID 30949203, 2019).
thyroid neoplasms (1 paper, 2022). "PAX2 stains similarly to PAX8; with the possibly useful difference of negative PAX2 staining in thyroid neoplasms, admittedly only reported in small series." (PMID 36428491, 2022).
uterine carcinoma (1 paper, 2021). A carcinoma involving a uterus. "Use of a panel of markers such as GATA3 and CD10 and awareness of the lack of specificity of PAX2 will help avoid misdiagnosis, particularly when MLA and other uterine carcinomas showing mesonephric-like differentiation are suspected." (PMID 33919505, 2021).
Wolf-Hirschhorn syndrome (1 paper, 2022). Wolf-Hirschhorn syndrome (WHS) is a developmental disorder characterized by typical craniofacial features, prenatal and postnatal growth impairment, intellectual disability, severe delayed psychomotor development, seizures, and hypotonia. "In our review summary, there were seven cases of low-birth-weight infants, two cases of intrauterine growth retardation, one case of PAX2 mutation, five cases of Wolf-Hirschhorn syndrome (partial deletion of chromosome 4), and two patients diagnosed with limbic renal syndrome." (PMID 35391889, 2022).
tumor (77 papers, 2008 to 2025). "The expression of an intron 9 containing PAX2 splice variant was analyzed in neoplastic B cell and solid tumor cell lines as well as in primary tumor samples by quantitative RT-PCR." (PMID 19467152, 2009). "The higher expression levels possibly correlate with a better prognosis due to the tumor’s less aggressive behavior and the loss of PAX2 expression might be linked to a more aggressive or invasive phenotypes." (PMID 40506992, 2025). "In addition, re-expression of PAX2 in PTEN-depleted FTE cells blunted tumor formation, suggesting that loss of PAX2 is important in PTEN-induced tumorigenesis." (PMID 33828085, 2021). "In addition, the rs45454293T-allele creates a binding site for the transcription factor PAX-2, a factor involved in development of renal epithelium by induction of tumor suppressor genes as well as in cell proliferation and carcinogenesis." (PMID 21445270, 2011). "Although it has been suggested that abnormal promoter methylation underlies PAX2 protein loss, this hypothesis lacks supporting evidence, and there have not been investigations establishing PAX2 as a functionally significant in vivo tumor suppressor." (PMID 40829174, 2025). "PAX2’s status as a tissue-specific oncodevelopmental factor is consistent with our results that promoter hypermethylation is not the underlying mechanism for PAX2 silencing, given that most tumor suppressor loci subject to CpG island hypermethylation are broadly expressed housekeeping genes." (PMID 40829174, 2025). "Consistent with findings in PDX models, the PAX2+ tumor harbored an approximately 15 kbp open chromatin region — indicative of a superenhancer — near the PAX2 promoter." (PMID 40829174, 2025). "This epigenetic switch from H3K27ac to H3K27me3 is likely to undergo positive selection, as we have shown that PAX2 is a tumor suppressor." (PMID 40829174, 2025). "Four primary cell populations were first identified using canonical cell markers: WT tumor cells (WT1, NCAM1, SIX1, SIX2, PAX2), cancer-associated fibroblasts (CAFs) (ACTA2, TAGLN, COL1A1, PDGFRB), endothelial cells (PECAM1, CLDN5, ENG, VWF) and immune cells." (PMID 40098972, 2025). "Xenograft assays comparing scrambled shRNA control with PAX2 shRNA showed that KD resulted in more rapid tumor growth and larger tumors." (PMID 40829174, 2025). "There is also evidence of a direct relationship between TGF-β1 signaling and PAX2 expression during RCC tumor progression." (PMID 40506992, 2025). "PAX2 is an oncodevelopmental tumor suppressor regulating endometrial gene expression via control of the enhancer landscape." (PMID 40829174, 2025). "In summary, these results provide formal genetic evidence that Pax2 is an in vivo EC tumor suppressor that synergizes with Pten, establishing mice as a useful model for additional investigations into the biology of Pax2 in EC." (PMID 40829174, 2025). "In vivo xenograft assays comparing empty and PAX2 vectors (with DOX-induced expression via drinking water) demonstrated that PAX2 reexpression resulted in tumor xenografts with slower growth and reduced size." (PMID 40829174, 2025). "PAX2 showed both high sensitivity (96.6%) and high (90.4%) specificity for MA when using a cutoff of >50% of tumor cells for normal expression." (PMID 38970797, 2024). "CnA-binding protein (CnABP) was found to be coexpressed with paired box 2 (PAX2) in the developing kidney in vitro, a crucial gene involved in kidney development and also a key regulator of Wilm’s tumor progression." (PMID 38999976, 2024).
tumor (continued). "Some studies have found that PAX2 has both oncogenic and inhibitory effects on invasion during tumor development." (PMID 37511191, 2023). "This, combined with the hypoxic conditions in the local tumor tissue microenvironment, has been shown to induce re-expression of PAX2." (PMID 37511191, 2023). "Employing this data, we verified that PAX2, PR and ERalpha levels are reduced in tumor samples (versus normal tissue) and they decreased even further throughout all stages of the disease." (PMID 35018885, 2022). "The relationship between PAX2 expression and the clinical stage, lymph node metastasis, and tumor differentiation level of HCC patients was further analyzed." (PMID 35028121, 2022). "It is of note, however, that two tumors in this study showed strong nuclear PAX2 immunoreactivity in approximately 20% tumor cells." (PMID 34441384, 2021). "Pax2 is related to chromosomal translocation in tumor cells and the development of kidney, central nervous system (CNS), and optic nerve, while Pax8 is involved in thyroid, CNS, and kidney cell development." (PMID 34824296, 2021). "The tumor cells showed focal nuclear PAX2 immunoreactivity with mild-to-moderate staining intensity." (PMID 33919505, 2021). "In particular, 20% tumor cells in these cases exhibited intense PAX2 expression in the small tubules and glands." (PMID 34441384, 2021). "In contrast, the consistent hypermethylation at CpG islands associated with genes such as HNF1β, PAX2, SOX9 and WNT9B implies that epigenetic control of nephrogenesis is dysregulated in a targeted fashion in Subgroup B tumours." (PMID 33012783, 2021). "This study showed compared with normal fimbria, expression of PAX2 protein as well as PAX2 gene was lower in fimbria with tumor limited to the fimbria and the expression was lowest in late stage tumors." (PMID 34314463, 2021). "In contrast, the remaining two cases showed moderate-to-strong nuclear PAX2 immunoreactivity in 30–70% tumor cells." (PMID 34441384, 2021). "Mechanistically, PAX2 and tamoxifen coexert an antitumoral effect by maintaining high levels of transcription of tumor suppressors that promote cell death." (PMID 32843722, 2020). "Now, we identified that PAX2 inhibits cell growth of ER+/HER2− tumor cells in a dose-dependent manner." (PMID 32843722, 2020). "This apparent selection against PAX2 expression within subpopulations of tumor cells seems counter-intuitive to the notion that PAX2 plays an oncogenic role in tumorigenesis." (PMID 29928489, 2018). "In RCC, loss of VHL and hypoxia has been shown to activate PAX2 expression, but the potential role of PAX2 expression in RCC at later stages of tumor development is less well understood." (PMID 29928489, 2018). "Pathology of tumors showed characteristic ELST morphology with immunoexpression of CK7, GFAP, S100, PAX-8, PAX-2, CA-9 in the tumor cells." (PMID 30340515, 2018). "Nevertheless, these findings represent the first evidence for direct promoter-mediated inhibition of PAX2 expression by TGF-β1 signalling in tumor cells." (PMID 29928489, 2018). "We propose that pathways involving TGF-β1 signalling, and subsequent down-regulation of PAX2 expression facilitate the switching of tumor cells from PAX2-mediated epithelial cell differentiation to more stem cell-like mesenchymal programs." (PMID 29928489, 2018). "PAX2 is expressed in multiple tumors, and its expression is essential for tumor cell survival in a variety of cancers, including cancers of the female reproductive tract." (PMID 27764784, 2016). "For the clear carcinomas with PAX2 nuclear positive staining, the percentage of tumor cells with positive staining varied from 10% to over 75%." (PMID 23502471, 2013). "Instead, the frequent chromosome 10 loss observed in chrRCC samples, and the significant correlation with Pax-2 immunoexpression categories, indicate that this genetic alteration is the major cause for PAX2 underexpression in this tumour subtype." (PMID 23890189, 2013).
tumor (continued). "Correlation analyses revealed similar trends in PAX2 expression at the protein or transcript levels and tumour grade, disclosing significant inverse correlations." (PMID 23890189, 2013). "Concerning pathological tumour stage, however, only PAX2 immunoexpression showed a significant inverse correlation, whereas the same trend was not apparent at the mRNA level." (PMID 23890189, 2013). "On the other hand, PAX2 expression could be involved in maintaining the epithelial characteristics of the tumor cells, in Low Malignant Potential (LMP) ovarian tumors." (PMID 40506992, 2025). "Thus, while 2 distinct tumor histotypes were observed in Pax2/Pten EC, often together, both fell within the spectrum of human EC." (PMID 40829174, 2025). "While Pax2 mice had normal uterine weights and Pten mice had increased uterine weights due to longer uterine horns rather than invasive cancers, Pax2/Pten mice had far higher uterine weights reflecting overt tumor burden." (PMID 40829174, 2025). "Western blot analysis of tumor lysates at the end of the experiment confirmed stable PAX2 KD." (PMID 40829174, 2025). "Mouse model establishes Pax2 as in vivo EC tumor suppressor that synergizes with Pten." (PMID 40829174, 2025). "To overcome these limitations and test the hypothesis that PAX2 is an EC tumor suppressor in the most rigorous in vivo genetic system, we explored the biological functions of Pax2 in genetically engineered mice." (PMID 40829174, 2025). "We analyzed 3 patient tumors: 1 PAX2+ (patient tumor 1), and 2 PAX2– (patient tumors 2 and 3)." (PMID 40829174, 2025). "In addition, its target gene PAX2 acts as a tumor suppressor in endometrial carcinogenesis, which is an accurate marker of precancerous endometrial hyperplasia." (PMID 35812749, 2022). "The transcription factor PAX2 is involved in tumor angiogenesis." (PMID 35615155, 2022). "Overexpressed miR-744 in drug-resistant cell-derived exosomes can further act as a mediator to induce the upregulation of miR-744 in normal tumor cells, thereby increasing the sensitivity of Sorafenib by inhibiting the protein expression of the downstream target paired box 2 (PAX2)." (PMID 33869059, 2021). "In contrast, expression of PAX2 decreased gradually as the tumor progressed to late stages." (PMID 34314463, 2021). "We evaluated demographic data and tumor characteristics regarding PAX2 and PAX8 expression." (PMID 34306127, 2021). "However, no research is currently available on the relationship between tumor size and PAX2 and PAX8 expression." (PMID 34306127, 2021). "Notably, we did not observe the direct association of TET3 with these factors, and found that several tumor suppressor genes (CDKN2B, ZIC2, and miR-196a) and oncogenes (PAX2, IL2RA, SOX11, and PAK7) were associated with TET3 in AML biology." (PMID 32209730, 2020). "Additionally, there is evidence of an interaction between PTEN and other key cell regulatory proteins contributing to tumor invasion, such as Paired box protein (PAX2)." (PMID 34322276, 2019). "Moreover, PAX2 protein is strongly expressed in primary CC-RCC in a high percentage (~66%) of tumor cells, and in CC-RCC metastases expression of PAX2 appears to be more intense and in a higher proportion (~80%) of tumor cells." (PMID 29928489, 2018). "The xenograft and parental RCC52 original patient tumor sections shared some similarity in terms of the area of clear cells in the majority of sarcomatoid cells, i.e. the areas of clear cells were always stained positively with anti-PAX2 antibody." (PMID 28121626, 2017). "PAX2 mutation may therefore cause a shift in PRC2 target genes, which would promote tumor progression." (PMID 27634879, 2016). "PAX2 is highly expressed in multiple tumors and is essential for tumor cell survival." (PMID 27764784, 2016). "Moreover, PAX2 has been reported to function as an oncogene, conferring proliferative and apoptosis inhibitory characteristics to cells in several tumour models, including RCTs." (PMID 23890189, 2013).
tumor (continued). "Further investigation of PAX2 in tumor suppression and mortality is warranted." (PMID 23502471, 2013). "Expression of PAX2 in these cells appears to be important for tumor cell survival." (PMID 23502471, 2013). "This might explain both the lower PAX2 mRNA levels and protein expression globally observed in this tumour subtype." (PMID 23890189, 2013). "However, PAX2 expression was frequently identified in neoplasia responsible for the growth and survival of cancer cells." (PMID 19467152, 2009). "Recently, a panel of 3 markers consisting of β-catenin, PAX2, and PTEN has been described as a potentially useful diagnostic adjunct in the diagnosis of intrauterine endometrioid neoplasia, where aberrancy for one or more of the markers is strongly associated with neoplasia." (PMID 39078313, 2025). "In this study we found the combination of scoring for HAND2, PTEN, and PAX2 was able to align staining patterns with diagnosis of EIN or HwA based on diagnostic criteria and might be useful in identifying those most likely to have benign disease." (PMID 36303676, 2022). "Therefore, by inhibiting the cell division and also by inducing apoptosis PAX2 and Tam might prevent the tumor growth and ultimately lead to more efficient Tam response." (PMID 32843722, 2020). "It is conceivable, however, that the therapeutic inhibition of PAX2 could induce tumor progression and metastasis in some cancer types, particularly if continued expression of PAX2 has a role in promoting epithelial differentiation and suppression of tumor metastasis in advanced stages of cancer." (PMID 29928489, 2018). "Thus, PAX2 could have both oncogenic and tumor suppression functions which will depend on the genetic content of the cancer cells." (PMID 23502471, 2013). "PAX genes from subgroups II (PAX2, PAX5, and PAX8) and III (PAX3 and PAX7) are involved in essential processes such as cell survival, motility, and tumor progression." (PMID 40506992, 2025). "PAX2 regulates genes involved in cell adhesion and the extracellular matrix (ECM), to promote tumor cell invasion and metastasis." (PMID 40506992, 2025). "Conversely, progesterone receptor (PR) was negative in the only tested case, as well as GATA-3, SALL-4, PTEN, PAX-2, AFP and calretinin, while ARID1A was retained in one case and another tumor has a CK7+/CK20− phenotype." (PMID 39996865, 2025). "A previous report suggested that the PAX2 promoter is normally hypermethylated but becomes unmethylated in EC, although this is opposite to MLH1 and other tumor suppressors subject to promoter hypermethylation." (PMID 40829174, 2025). "In HGSC, PAX2 and PAX8 can enhance tumor vascularization via their interaction with SOX17, another developmental factor." (PMID 40506992, 2025). "These contain known cancer-testis antigen genes (MEGA5, MEGA1, TEX15, PNMA5 and ROR1) and a number of new candidate genes (PAX2, NTN4, NTNG2 and PDE10A), these genes can be used as tumour markers or potential therapeutic targets with some clinical value." (PMID 37994961, 2023). "Analysis of the online data revealed that PAX2 and PAX8 were expressed at relatively high levels in RCC tumor tissues compared to other PAX genes, while PAX6 was expressed at lower but still significant levels." (PMID 37511191, 2023). "PAX2 predictive efficacy for HCC and its correlation with clinical stage, lymph node metastasis, tumor differentiation level, and HCC-related serum marker levels were analyzed." (PMID 35028121, 2022). "We also evaluated PAX2 and PAX8 immunostainings related to age, gender, tumor size, and histomorphologic tumor characteristics." (PMID 34306127, 2021). "We were able to rule out the possibility of mixed EC and MLA because most of the tumor cells with GATA3 and PAX2 expression demonstrated moderate-to-strong nuclear immunoreactivity for ER and PR." (PMID 34829389, 2021).